ASPSCR1 (ASPSCR1 tether for SLC2A4, UBX domain containing)
Description:
Tethering protein that sequesters GLUT4-containing vesicles in the cytoplasm in the absence of insulin. Modulates the amount of GLUT4 that is available at the cell surface (By similarity). Enhances VCP methylation catalyzed by VCPKMT.
Synonyms: ASPL; RCC17; TUG; UBXD9; UBXN9; ASPS; ASPCR1
Tractability: Small molecule: a structure with a bound ligand is known. Antibody: its Gene Ontology location is reachable by antibodies, with high confidence; UniProt places it where antibodies can reach, with medium confidence. PROTAC: ubiquitination databases record sites on it; its protein half-life has been measured.
Gene: Protein-coding gene on chromosome 17 (81,976,807 to 82,017,406, forward strand). Ensembl gene ENSG00000169696.
Subcellular location: Endomembrane system; Endoplasmic reticulum-Golgi intermediate compartment membrane; Cytoplasm; Nucleus
Subcellular location (Human Protein Atlas): Nucleoplasm; Plasma membrane; Vesicles
Pathways (Reactome):
Vesicle-mediated transport: Translocation of SLC2A4 (GLUT4) to the plasma membrane
Gene Ontology:
Molecular function: methyltransferase regulator activity; protein binding
Biological process: peptidyl-lysine trimethylation; ERAD pathway; glucose homeostasis; intracellular protein transport
Cellular component: intracellular protein-containing complex; nucleoplasm; cytoplasm; nucleus; vesicle membrane; cytoplasmic side of plasma membrane; cytosol; endomembrane system; endoplasmic reticulum-Golgi intermediate compartment membrane; perinuclear region of cytoplasm
Genetic constraint (gnomAD): Loss-of-function variants: 55 observed, 65.5 expected, observed/expected ratio (o/e) 0.84, 90% interval 0.68 to 1.05. The upper end of that interval is the gene's LOEUF score, 1.05, which puts it in group 4 of 6, group 1 being the genes least tolerant of losing a copy. Missense variants: 741 observed, 716.78 expected, observed/expected ratio (o/e) 1.03, 90% interval 0.97 to 1.1. Synonymous variants: 343 observed, 307.48 expected, observed/expected ratio (o/e) 1.12, 90% interval 1.02 to 1.22.
Homologues: Orthologues: chimpanzee ASPSCR1 (92% identical), macaque ASPSCR1 (89% identical), mouse Aspscr1 (79% identical), guinea pig ASPSCR1 (76% identical), pig ASPSCR1 (75% identical), dog ASPSCR1 (73% identical), rat Aspscr1 (73% identical), tropical clawed frog aspscr1 (49% identical), zebrafish aspscr1 (48% identical), Drosophila melanogaster CG33722 (26% identical), Caenorhabditis elegans asps-1 (23% identical). Paralogues in human: UBXN6 (16% identical).
Diseases named in the same sentence as ASPSCR1 in open-access papers:
ASPSCR1 is named in the same sentence as 35 diseases in open-access papers, as found by Europe PMC text mining. Sharing a sentence is not in itself a finding about the gene and the disease. The quoted sentences say what the papers report.
alveolar soft part sarcoma (22 papers, 2009 to 2025). An alveolar soft part sarcoma occurring in adults. "Some cases of alveolar soft tissue sarcomas have been found to be caused by the fusion of ASPSCR1 and TFE3." (PMID 37510264, 2023). "Molecular analysis using NGS sequencing identified germline variants in the RYR1 and ASPSCR1 (alveolar soft part sarcoma) genes." (PMID 37510264, 2023). "Alveolar soft part sarcoma (ASPS) often carries a translocation between ASPSCR1 and TFE3 genes, resulting in a fusion protein that transcriptionally upregulates MET." (PMID 37213274, 2023). "ASPL (alveolar soft-part sarcoma locus; also known as UBXD9, TUG, or ASPSCR1) is a unique p97 adaptor protein that regulates p97 activity by disassembling the p97 hexamer into smaller oligomers." (PMID 36656859, 2023). "Pull-down assays were used to confirm the interaction of rCsNOSIP with alveolar soft part sarcoma (ASPSCR-1) and sirtuins 5 (Sirt-5)." (PMID 37948465, 2023). "Lactate uptake by tumors feeds their oxidative metabolism and requires the importer MCT1, a marker of mitochondrial activity and stemness in cancer and a target gene of the fusion protein ASPSCR1/TFE3 in alveolar soft part sarcoma (ASPS)." (PMID 34294128, 2021). "ASPSCR1 is a candidate gene for alveolar soft part sarcoma (ASPS), a rare type of soft tissue sarcoma that typically occurs in young patients and often spreads to the lungs, brain and bone." (PMID 31257439, 2019). "Diagnoses included ASPSCR1::TFE3 alveolar soft part sarcoma; WWTR1::CAMTA1 epithelioid hemangioendothelioma; INI-1 deficient epithelioid sarcoma; EWSR1::NR4A3 extra-skeletal myxoid chondrosarcoma; and low-grade ARHGAP23::FER spindle cell malignancy, a novel fusion-driven sarcoma." (PMID 39941809, 2025). "ASPSCR1 and Transcription factor E3 (TFE3) fusion is observed in tumors including alveolar soft part sarcoma (ASPS) and Xp11-associated renal cell carcinoma." (PMID 36291758, 2022). "ASPSCR1, through its fusion with TFE3, plays a pivotal role in the development of alveolar soft part sarcoma by acting as an aberrant transcriptional transactivator, leading to deregulated transcription and oncogenesis." (PMID 40297177, 2025). "It is also called ASPSCR1 or ASPL, reflecting its involvement in chromosomal translocations in alveolar soft part sarcomas, and UBXD9 or UBXN9, reflecting its membership in a family of UBX domain -containing proteins." (PMID 36246906, 2022). "The t(X,17) chromosomal translocation, generating the ASPSCR1::TFE3 fusion oncoprotein, is the singular genetic driver of alveolar soft part sarcoma (ASPS) and some Xp11-rearranged renal cell carcinomas (RCCs), frustrating efforts to identify therapeutic targets for these rare cancers." (PMID 38326311, 2024). "ASPS is characterised by the pathognomonic unbalanced, non-reciprocal translocation t(X;17)(p11:q25), fusing the alveolar soft part sarcoma chromosome region candidate 1 (ASPSCR1) gene on chromosome 17 to the transcription factor binding to IGHM enhancer 3 (TFE3) gene on the X chromosome." (PMID 31722230, 2020).
renal cell carcinoma (9 papers, 2018 to 2024). "The morphology of renal cell carcinoma cells with the ASPSCR1::TFE3 fusion is often similar to that of ASPS cells." (PMID 38291475, 2024). "One of the most common gene fusions is ASPSCR1::TFE3, and this fusion requires differential diagnosis from translocation-associated renal cell carcinoma (RCC)." (PMID 38872175, 2024). "TFE3 positivity is also observed; however, renal cell carcinomas with the ASPSCR1::TFE3 fusion also express CK and EMA epithelial markers and are positive for CD10 and RCC." (PMID 38291475, 2024). "However, the first description of TFE3-rearranged renal cell carcinoma is commonly considered in 2001 by Argani who reported eight renal tumors arising in children characterized by a t(X;17)(p11.2;q25) translocation, which fuses the ASPL/ASPSCR1 and TFE3 genes." (PMID 39410016, 2024). "Previous studies identified numerous ASPSCR1::TFE3 targets that are involved in growth signaling, lysosomal functions, autophagy, and angiogenesis in both ASPS and fusion-positive renal cell carcinoma, with the latter exhibiting a vascular structure similar to that of ASPS21,22,24,25,36." (PMID 37029109, 2023). "Although over the past 30 years, numerous fusion partners have been identified in TFE3-rearranged renal cell carcinoma and PEComa, ASPL/ASPSCR1, PRCC, SFPQ, NONO, and MED15 remain the most frequent in both groups of neoplasms." (PMID 39410016, 2024). "TFE3-rearranged renal cell carcinoma, as the name indicates, harbors TFE3 gene translocation which fuses with one of several other genes, such as ASPL (ASPSCR1), PRCC, SFPQ, CLTC, PARP14, RBM10, NONO, and MED15." (PMID 35980471, 2022).
soft part sarcoma (6 papers, 2019 to 2025). "The most common partners involved in TFE3-tRCC are PRCC (papillary renal cell carcinoma) with t(X;1)(p11.2;q21.2), ASPSCR1(ASPL) (alveolar soft part sarcoma locus) with the t(X;17)(p11.2;q25) and SFPQ (splicing factor proline- and glutamine-rich protein) with t(X;1)(p11.2;p34)." (PMID 35886994, 2022). "In addition, it was recently shown that in alveolar soft part sarcoma, the expression of the fusion transcription factor ASPSCR1::TFE3 is required for in vivo tumor development via angiogenesis, orchestrating higher-ordered angiogenesis via super-enhancers activity." (PMID 37510264, 2023).
sarcoma (4 papers, 2022 to 2025). A usually aggressive malignant neoplasm of the soft tissue or bone. "Like other sarcoma-associated fusion genes, ASPSCR1::TFE3 is essential for transforming target cells to induce ASPS in vivo." (PMID 37029109, 2023). "The N-terminal portion of TFE3 is being replaced by ASPSCR1 (ASPL) sequences, while retaining its DNA-binding domain, and is implicated in transcriptional deregulation and pathogenesis of this type of sarcoma." (PMID 35682989, 2022). "Altogether, cross-species comparison of transcriptome, methylome, and histology data revealed a coherent picture, indicating conservation of human sarcoma biology across the sarcoma EPO-GEMM cohort, especially for bona fide fusion-driven sarcomas SS18::SSX, NTRK-Mono, PAX3::FOXO1 and ASPSCR1::TFE3." (PMID 40523919, 2025).
alveolar rhabdomyosarcoma (2 papers, 2023). A rapidly growing malignant mesenchymal neoplasm. "Taken together, these two pieces of evidence imply a possible role for the detected germline ASPSCR1 variant in rhabdomyosarcoma development." (PMID 37510264, 2023). "Here, we report the case of a patient with an RYR1 pathogenic variant associated with MH and cores who developed an alveolar rhabdomyosarcoma associated with a germline variant in the cancer predisposition gene ASPSCR1 (Alveolar Soft Part Sarcoma Chromosomal Region Candidate 1)." (PMID 37510264, 2023). "We presented the case of a patient with MH, cores, and alveolar rhabdomyosarcoma with a germline RYR1 pathogenic variant and a germline VUS in the ASPSCR1 gene." (PMID 37510264, 2023).
breast carcinoma (1 paper, 2020). "However, ERBB2 amplification was often observed as arm-level events or separate from pter-located GISTIC peaks, including ASPSCR1 and RNF213, which is in stark contrast to the minimal amplification of ERBB2 observed in human breast cancers (inlet)." (PMID 32680987, 2020).
prostate carcinoma (1 paper, 2025). A carcinoma that arises from epithelial cells of the prostate gland. "Current research on SPEG, ASPSCR1, and CEP89 in prostate cancer is relatively limited." (PMID 40297177, 2025).
squamous carcinomas (1 paper, 2022). "Chu and colleagues described the mutational characterization from whole exome sequencing of a case of PSCCT, including TMPRSS2, BRCA1, ASPSCR1, and others, but the identified driver mutations common in squamous carcinomas are absent." (PMID 36329478, 2022).
tumor (16 papers, 2009 to 2024). "Significant tumor-growth inhibition in vivo by ASPSCR1::TFE3 loss indicates the importance of co-proliferation between tumor cells and blood vessels in ASPS." (PMID 37029109, 2023). "The deletions of ASPSCR1 most likely resulted in the loss of function and decreased expression of ASPSCR1, suggesting its role as a potential tumor suppressor gene in the development of HCC." (PMID 25469175, 2014). "The similar tumor suppression and angiogenesis phenotypes and gene expression profiles between ASPSCR1::TFE3 loss and the JQ1 treatment suggests the critical role of SEs modulated by ASPSCR1::TFE3, although the mechanism by which Brd4-inhibition targets certain SEs awaits clarification." (PMID 37029109, 2023). "Interestingly, the expression of ASPSCR::TFE3 is dispensable for tumor-cell maintenance in vitro; however, its expression is required for in vivo tumorigenesis and angiogenesis, and ASPSCR1::TFE3-expression loss induces drastic modifications in SE distribution." (PMID 37029109, 2023). "ASPSCR1::TFE3 ChIP-seq on mouse tumor cells and patient-derived cells determined that the fusion oncoprotein highly colocalized with the active histone mark H3K27ac and bound near genes related to blood vessel development." (PMID 38916046, 2024). "ASPSCR1 gene, the interacting gene of EPI, can translocate with TFE3 gene and results in a ASPSCR1-TFE3 fusion protein, which causes the tumor hypoxia and angiogenesis in alveolar soft part sarcoma." (PMID 38662077, 2024). "Mouse tumor presentation remained consistent even when ASPSCR1::TFE3 was expressed under a tissue-specific promoter." (PMID 38916046, 2024). "During 5 days of co-culturing, significant HUVEC sprouting toward the tumor spheroids of ASPS cells occurred; however, the sprouting effect was significantly suppressed by Rab27a or Sytl2 knockout and ASPSCR1::TFE3-expression loss." (PMID 37029109, 2023). "The interaction of rCsNOSIP with ASPSCR-1 and Sirt-5, two screened proteins closely related to tumor progression, was confirmed by GST-pull down assay." (PMID 37948465, 2023). "The present study demonstrates the essential role of the ASPSCR1::TFE3 driven pathways in tumor development and angiogenesis." (PMID 37029109, 2023). "As shown by ASPSCR1::TFE3-expression loss and JQ1 treatment, tumor-growth suppression by each knockout cell was accompanied by significant angiogenic inhibition." (PMID 37029109, 2023). "ASPSCR-1 and Sirt-5, which may be closely related to tumor migration had been identified, were selected according to the bioinformatics analysis." (PMID 37948465, 2023). "Here, we find that the expression of ASPSCR1::TFE3, the fusion transcription factor causatively associated with ASPS, is dispensable for in vitro tumor maintenance; however, it is required for in vivo tumor development via angiogenesis." (PMID 37029109, 2023). "Using antibodies against both ASPSCR1 and human TFE3, we documented expression of the fusion protein in tumor lysates." (PMID 38386415, 2024). "Surprisingly, UBXN10 expression was downregulated in the majority of tumours except for KIRP and BRCA, while ASPSCR1 expression was upregulated in tumours except for KICH, KIRC, and THCA." (PMID 38365777, 2024). "ASPSCR1::TFE3 also upregulates genes important for angiogenesis and tumor metastasis, such as PDGFB, ANGPTL2, and GPNMB17,24,25, suggesting that ASPSCR1::TFE3 plays a central role in the angiogenesis characteristic of ASPS." (PMID 37029109, 2023). "Regarding molecular rearrangements, among the neoplasms with available data, the SFPQ/PSF::TFE3 fusion was the most frequent genetic alteration found (14 cases, 74%), followed by ASPL/ASPSCR1::TFE3 (3 cases, 16%), RBM10::TFE3 (1 case, 5%), and MED15:TFE3 (1 case, 5%)." (PMID 39410016, 2024). "Therefore, epigenetic CRISPR screening with dCas9-KRAB was performed to identify ASPSCR1::TFE3 targets that are required for angiogenesis and in vivo tumor growth." (PMID 37029109, 2023).
cancer (15 papers, 2014 to 2024). A tumor composed of atypical neoplastic, often pleomorphic cells that invade other tissues. "In addition, loss of function and decreased expression of ASPSCR1 has also been implicated in synthetic lethal interactions in cancer." (PMID 25469175, 2014). "For example, most cancer tissues exhibit weak to moderate cytoplasmic and/or nuclear immunoreactivity in the ASPSCR1, UBXN2A, UBXN10, UBXN1, FAF1, FAF2, UBXD2B proteins." (PMID 38365777, 2024). "All carcinomas with ASPL/ASPSCR1::TFE3 fusion were classified into the high angiogenesis/stroma/proliferation cluster, whereas half of the MED15::TFE3 and SFPQ/PSF::TFE3 tumors were included in the cluster enriched for EMT, apical junction, TGF-β, WNT catenin, and hypoxia signaling." (PMID 39410016, 2024). "For example, never-smokers displayed a greater proportion of hypomethylated differentially methylated regions (hypoDMRs) and a greater number of recurrently hypomethylated promoters, including those of ASPSCR1, TOP2A, DPP9, and USP39, all previously linked to cancer." (PMID 37742993, 2023). "However, no direct evidence of differential expression of ASPSCR1 linked to increase risk of progression has been reported in cancers previously." (PMID 36291758, 2022). "We demonstrate that VCP is a likely obligate co-factor of ASPSCR1::TFE3, one of the only such fusion oncoprotein co-factors identified in cancer biology." (PMID 38326311, 2024). "ASPSCR1 (↑2.6X twins), is a UBX domain containing tether for SLC2A4, which has a known fusion protein to TFE3 that is involved in certain cancers." (PMID 33115496, 2020). "These deletions contained known cancer genes based on the Sanger Census cancer gene list, including FGFR3, RECQL4, NOTCH1, PTEN, TSC2, and/or ASPSCR1 which suggested their roles as tumor suppressor genes in the development of HCC." (PMID 25469175, 2014). "Finally, ASPSCR1::TFE3 and VCP demonstrate co-dependence for cancer cell proliferation and tumorigenesis in vitro and in ASPS and RCC mouse models, underscoring VCP’s potential as a novel therapeutic target." (PMID 38326311, 2024).
ASPSCR1 also shares sentences with these, for which no sentence is quoted: infection (3 papers); Insulin resistance (3); epithelioid hemangioendothelioma (2); metabolic disease (2); Obesity (2); amyotrophic lateral sclerosis (1); cholangiocarcinoma (1); clear cell renal cell carcinoma (1); diabetes (1); epithelioid sarcoma (1); glioma (1); Hypertension (1); leukemia (1); lumbago (1); lung carcinoma (1); mild cognitive impairment (1); neuroblastoma (1); ossifying fibromyxoid tumor (1); Paget disease (1); papillary renal cell carcinoma (1); renal tumors (1); soft tissue tumors (1); synovial sarcoma (1); type 2 diabetes (1); virus infection (1).